C9orf72 (C9orf72-SMCR8 complex subunit)
Diseases named in the same sentence as C9orf72 in open-access papers (continued):
Sharing a sentence is not in itself a finding about the gene and the disease.
frontotemporal dementia (continued). "Importantly, the involvement of R-loops in expansion diseases is not limited to trinucleotide repeats, since R-loops associated with expanded hexanucleotide GGGGCC repeats in C9orf72 contribute to the molecular event leading to amyotrophic lateral sclerosis (ALS) and frontotemporal dementia (FTD)." (PMID 25233079, 2014). "This targeted approach has proven effective in identifying pathogenic mutations in familial neurodegenerative disorders, such as the C9orf72 repeat expansion in ALS and frontotemporal dementia (FTD)." (PMID 40004464, 2025). "Clinically, ALS intersects with frontotemporal dementia (FTD) in up to 50% of the cases, driven by shared TDP-43 pathology and C9orf72 hexanucleotide expansions." (PMID 40283201, 2025). "Micro-satellite repeat expansion of the 5’ GGGGCC 3’ sequence in the C9orf72 gene is the most common monogenic form of amyotrophic lateral sclerosis (ALS) and frontotemporal dementia (FTD)." (PMID 41394638, 2025). "In the neurodegenerative diseases amyotrophic lateralsclerosis (ALS) and frontotemporal dementia (FTD), the expansion ofthe intronic hexanucleotide repeat (GGGGCC)n in the C9orf72 locus is the most common hereditarytract." (PMID 39555660, 2024). "A number of proteins has been explored as potential fluid biomarkers for frontotemporal dementia and amyotrophic lateral sclerosis, particularly those relating to frontotemporal dementia/amyotrophic lateral sclerosis brain pathology, e.g. TDP-43, tau, C9ORF72 or SOD1." (PMID 35202463, 2022). "Chantal Sellier and colleagues generated the first zebrafish model related to SCA2 while they were studying the c9orf72 gene, a gene responsible of amyotrophic lateral sclerosis and frontotemporal dementia (ALS-FTD)." (PMID 33671313, 2021). "Finally, genetic testing for mutations in genes commonly associated with frontotemporal lobar degeneration (FTLD) (MAPT, GRN, C9orf72) was negative." (PMID 33310885, 2020). "Interestingly the IR-based pathomechanism turned out to be relevant for other diseases with intronic GC-rich but not A/AT-rich microsatellite mutations including C9orf72-linked amyotrophic lateral sclerosis with frontotemporal dementia (C9-ALS/FTD) and Fuchs endothelial corneal dystrophy (FECD)." (PMID 32708277, 2020). "A repeat expansion in C9orf72 is responsible for the characteristic neurodegeneration in amyotrophic lateral sclerosis (ALS) and frontotemporal dementia (FTD) in a still unresolved manner." (PMID 32876811, 2020). "More recently, in familial amyotrophic lateral sclerosis (ALS) and frontotemporal dementia (FTD), a hexanucleotide block (CCGGGG)n in the C9orf72 locus which is normally a few tens of repeats in size has been shown to expand to thousands of base pairs." (PMID 31475042, 2019). "Aberrant methylation of the C9orf72 promoter region has been observed in repeat expansion carriers with amyotrophic lateral sclerosis (ALS) and frontotemporal dementia (FTD)." (PMID 31680172, 2019). "Most frequent genetic cause of amyotrophic lateral sclerosis (ALS) and frontotemporal dementia (FTD), is a largely increased number of d(G4C2)n•(G2C4)n repeats located in the non-coding region of C9orf72 gene." (PMID 30277522, 2018). "The interaction of C9orf72 products and TDP-43 in frontotemporal dementia is one recent candidate but the application need not be restricted to diseases with two protein pathogens; the role of the second morphogen in the Turing model might be taken by a non-pathogenic tissue factor." (PMID 28424609, 2017). "Dysregulation of RNA metabolism represents an important pathogenetic mechanism in both amyotrophic lateral sclerosis (ALS) and frontotemporal dementia (FTD) due to the involvement of the DNA/RNA-binding proteins TDP-43 and FUS and, more recently, of C9ORF72." (PMID 27151080, 2016). "We are therefore unable to present this transgenic mouse as model for C9orf72 related amyotrophic lateral sclerosis (ALS) and frontotemporal dementia (FTD)." (PMID 27938413, 2016).
frontotemporal dementia (continued). "It was related a repeat expansion in C9orf72 hexanucleotide in 6% of sporadic ALS and 44% of familiar ALS patients of European ancestry, with younger age at onset, shorter disease duration and higher frequency of Frontotemporal Dementia, in different ethnic populations." (PMID 26517122, 2015). "Repeat-associated non-AUG (RAN) translation at expanded GGGGCC repeats in the C9orf72 gene produces dipeptide repeat (DPR) proteins that are implicated in amyotrophic lateral sclerosis and frontotemporal dementia (C9-ALS/FTD)." (PMID 41231952, 2025). "Univariate association testing of C9orf72 expansion carriers showed that they have significantly poorer ALS-Specific ECAS scores; this finding parallels other studies and supports a link between C9orf72 and MND-FTD (Motor Neuron Disease with Frontotemporal Dementia) spectrum disorders." (PMID 38852112, 2024). "Moreover, the binding of an RNA, derived from a hexanucleotide repeat expansion (HRE), (GGGGCC)n, in the noncoding region of C9orf72, with NCL, could be a culprit behind amyotrophic lateral sclerosis and frontotemporal dementia via the aggravation of nucleolar stress." (PMID 36768455, 2023). "The most prevalent genetic cause of amyotrophic lateral sclerosis (ALS) and frontotemporal dementia (FTD) is the hexanucleotide repeat expansion of GGGGCC in the non-coding region of the first intron of the C9ORF72 gene." (PMID 37696852, 2023). "The most common inherited cause of two genetically and clinico-pathologically overlapping neurodegenerative diseases, amyotrophic lateral sclerosis (ALS) and frontotemporal dementia (FTD), is the presence of expanded GGGGCC intronic hexanucleotide repeats in the C9orf72 gene." (PMID 35164882, 2022). "The mechanistic underpinnings of C9orf72 in cellular toxicity and ultimately neuronal degeneration dependent Amyotrophic Lateral Sclerosis and Frontotemporal Dementia (ALS/FTD) emphasized the pathologic effects of POM121 depletion downstream of G4C2 repeat RNA expression." (PMID 34970494, 2021). "Nucleolar stress has been implicated in C9orf72 amyotrophic lateral sclerosis (ALS) and frontotemporal dementia (FTD), but this has not been specifically studied in sporadic ALS (SALS)." (PMID 33588953, 2021). "In addition, we investigated a cohort of C9orf72 negative patients (n = 2634) affected by frontotemporal dementia and/or amyotrophic lateral sclerosis; and also found that the AA-genotype of rs9357140 was associated with a later age of onset (adjusted P = 0.007 for recessive model)." (PMID 30252044, 2018). "A recent report suggested that ATTR in CSF was upregulated in patients with AD or frontotemporal dementia (FTD) involving mutant C9orf72 in comparison to disease control groups and control groups without neurological diseases and without mutant C9orf72." (PMID 31216785, 2019). "Amyotrophic lateral sclerosis (ALS) and frontotemporal dementia (FTD) are distinct neurodegenerative diseases that overlap in clinical presentation, neuropathology, and genetic underpinnings (e.g., C9orf72), yet the molecular basis for this overlap is not well understood." (PMID 29191947, 2018). "In addition, compared to control subjects the expression levels of PML, Ubc9, and SUMO1 were also not significantly different in the frontal cortex tissue from a cohort of patients affected by Frontotemporal lobar degeneration (FTLD), regardless of the C9orf72 repeat expansion." (PMID 37454169, 2023).
amyotrophic lateral sclerosis (565 papers, 2012 to 2026). Amyotrophic lateral sclerosis (ALS) is a neurodegenerative disease characterized by progressive muscular paralysis reflecting degeneration of motor neurons in the primary motor cortex, corticospinal tracts, brainstem and spinal cord. "We investigated the effects of C9orf72 mutation carriership on peripheral nerve excitability in asymptomatic individuals from families with a history of C9orf72 amyotrophic lateral sclerosis (ALS) and patients." (PMID 40923569, 2025). "Further, we replicated the association between amyotrophic lateral sclerosis and C9orf72 (rTWAS and joint Z = 5.4, rTWAS and joint P = 6.8 x 10-8, rTWAS Bonferroni P = 5.49 x 10-4, PIP = 1.0), one of the most well-known genetic risk factors for this condition." (PMID 39401554, 2025). "The main genetic cause of amyotrophic lateral sclerosis is a hexanucleotide repeat expansion within C9orf72." (PMID 39315308, 2024). "A hexanucleotide GGGGCC repeat expansion in the C9orf72 gene is the most frequent genetic cause of amyotrophic lateral sclerosis (ALS) and frontal temporal dementia (FTD)." (PMID 39282230, 2024). "Repeat expansions of C9orf72 are the most common known genetic cause of amyotrophic lateral sclerosis (ALS)." (PMID 38791054, 2024). "We also assayed CSF of 17 additional symptomatic C9orf72 mutation carriers from the Northeast Amyotrophic Lateral Sclerosis (NEALS) Consortium." (PMID 38278991, 2024). "Activation of Rab39A is catalyzed by C9orf72, a guanine exchange factor associated with amyotrophic lateral sclerosis and familial frontotemporal dementia." (PMID 37821429, 2023). "Between November 2011 and December 2020, clinical and genetic characteristics of n = 248 patients with amyotrophic lateral sclerosis carrying C9orf72 mutations were collected from the clinical and scientific network of German motoneuron disease centres." (PMID 37006326, 2023). "Corroborating the theory of oligogenic causation in amyotrophic lateral sclerosis, we found a co-occurrence of pathogenic variants in 10 patients (0.4%) with 7 being C9orf72 hexanucleotide repeat expansion carriers." (PMID 37223130, 2023). "Here, we first compared 683 unrelated amyotrophic lateral sclerosis cases and 3,196 controls with Finnish ancestry to find best single nucleotide polymorphisms that tag the C9orf72 hexanucleotide repeat expansion and intermediate-length alleles." (PMID 36936421, 2023). "The objective was to describe and analyse the clinical and genetic features of amyotrophic lateral sclerosis patients with C9orf72 mutations in a large population." (PMID 37006326, 2023). "C9orf72 repeat expansions are also the most common genetic cause of amyotrophic lateral sclerosis (ALS)." (PMID 36967384, 2023). "Overall, n = 248 patients with amyotrophic lateral sclerosis carrying a mutation in the C9orf72 gene were identified and included in the study." (PMID 37006326, 2023). "Subsequently, TMEM106B polymorphisms have been associated with FTLD caused by C9orf72 mutations, cognitive impairment in Amyotrophic lateral sclerosis (ALS) and Parkinson’s disease (PD), and Alzheimer’s disease (AD)." (PMID 35287730, 2022). "Another example is from amyotrophic lateral sclerosis (ALS) which is associated with a GC-rich sequences from the (GGGGCC) repeats expansion in the C9ORF72 gene." (PMID 36107769, 2022). "These disorders include well known conditions, such as Huntington's disease, as well as C9orf72-associated frontal lobe dementia and amyotrophic lateral sclerosis." (PMID 35182509, 2022). "For example, GGGGCC is a hexanucleotide STR motif in C9orf72 that is associated with amyotrophic lateral sclerosis (ALS), while CAG is a well-known trinucleotide repeat motif in several genes associated with repeat expansion disorders." (PMID 35484600, 2022). "In fact, Gly–Ala repeat inclusions are associated with C9orf72-related amyotrophic lateral sclerosis and sequester cell machinery." (PMID 34537246, 2021).
amyotrophic lateral sclerosis (continued). "Mutation of C9ORF72 is the most common genetic cause of amyotrophic lateral sclerosis (ALS) and frontal temporal degeneration (FTD), which is attributed to both a gain and loss of function." (PMID 34145292, 2021). "Large hexanucleotide repeats in C9orf72 have widely been proven to be the most common genetic risk factors for amyotrophic lateral sclerosis (ALS) and FTD." (PMID 34360863, 2021). "Glycine-alanine dipeptide repeats (GA DPRs) translated from the mutated C9orf72 gene have recently been correlated with amyotrophic lateral sclerosis (ALS)." (PMID 36697556, 2021). "The C9orf72 hexanucleotide repeat expansion is the commonest known genetic mutation in amyotrophic lateral sclerosis." (PMID 32226938, 2020). "A hexanucleotide repeat expansion within the C9orf72 gene is the most common genetic cause of amyotrophic lateral sclerosis (ALS) and its discovery has revolutionized our understanding of this devastating disease." (PMID 33096681, 2020). "A pathogenic GGGCCC hexanucleotide expansion in the first intron/promoter region of the C9orf72 gene is the most common mutation associated with amyotrophic lateral sclerosis (ALS)." (PMID 32678027, 2020). "Relationship between pathogenic C9orf72 expansion and phenotype, site onset, family history, therapy, and others comorbidities in patients with amyotrophic lateral sclerosis." (PMID 31156370, 2019). "A hexanucleotide repeat expansion in the C9orf72 gene is the most common cause of inherited forms of the neurodegenerative disease amyotrophic lateral sclerosis (ALS)." (PMID 28720882, 2017). "An expanded hexanucleotide repeat in a noncoding region of the C9orf72 gene is a major cause of amyotrophic lateral sclerosis (ALS), accounting for up to 40% of familial cases and 7% of sporadic ALS in European populations." (PMID 27097283, 2016). "A majority of familial frontotemporal lobar dementia and amyotrophic lateral sclerosis cases are associated with a large repeat expansion in a non-coding region of the C9ORF72 gene." (PMID 26408000, 2015). "GGGGCC repeat expansions of C9orf72 represent the most common genetic variant of amyotrophic lateral sclerosis and frontotemporal degeneration, but the mechanism of pathogenesis is unclear." (PMID 24866055, 2014). "While C9orf72 repeat expansions are connected to changed ER–mitochondria contacts in amyotrophic lateral sclerosis (ALS), pathogenic mutations in TDP-43 and FUS disrupt calcium signaling and mitochondrial bioenergetics by interfering with MAM-resident tethering proteins." (PMID 41002898, 2025). "In a model of amyotrophic lateral sclerosis (ALS) caused by C9orf72 gene mutations, the pathogenic poly-dipeptide GA50 directly binds to and inhibits SQOR, leading to excessive NLRP3 inflammasome activation in microglia and consequent mitochondrial dysfunction." (PMID 41210256, 2025). "C9orf72 is the most common familial gene associated with amyotrophic lateral sclerosis (ALS)." (PMID 38495583, 2024). "The non-coding hexanucleotide GGGGCC repeat expansion mutation in the chromosome 9 open reading frame 72 (C9orf72) gene is a major genetic cause of amyotrophic lateral sclerosis (ALS), a progressive and fatal neurodegenerative disorder characterised by a loss of motor neurons and paralysis." (PMID 38110419, 2023). "We screened 2340 sporadic amyotrophic lateral sclerosis patients from the German Network for motor neuron diseases for variants in 36 amyotrophic lateral sclerosis-associated genes using targeted next-generation sequencing and for the C9orf72 hexanucleotide repeat expansion." (PMID 37223130, 2023). "The hexanucleotide GGGGCC repeat expansion in C9orf72 (chromosome 9 open reading frame 72, 9p21.2) is most commonly associated with amyotrophic lateral sclerosis and frontotemporal dementia, but has also been detected in rare cases of PD, Alzheimer’s Disease, psychosis and atypical parkinsonism." (PMID 36765380, 2023).
amyotrophic lateral sclerosis (continued). "Several proof-of concept studies have shown promising results in C9orf72 expansions, fused in sarcoma-linked amyotrophic lateral sclerosis, Huntington’s disease and spinocerebellar ataxia type 1, 3, and 7 mouse models and non-human primates as well as in phase I clinical trials." (PMID 36746939, 2023). "Finally, analysis of human post-mortem brains confirmed a paucity of parvalbumin interneurons in the prefrontal cortex in sporadic amyotrophic lateral sclerosis and amyotrophic lateral sclerosis linked to C9orf72 mutations." (PMID 34136812, 2021). "Similarly, the expression c9orf72 gene was inhibited due to the formation of G-quadruplex structure in the non-coding region of its mRNA and causes Amyotrophic lateral sclerosis (ALS), a neurodegenerative disease." (PMID 26896846, 2016). "Box A ‐ dynamic and time‐averaged (static) resting state MEG metrics extracted from four participant groups: symptomatic amyotrophic lateral sclerosis (ALS), asymptomatic C9orf72 expansion carriers, asymptomatic SOD1 variant carriers, and healthy controls." (PMID 41042072, 2025). "Cytoplasmic mislocalisation and nuclear depletion of TDP-43 are pathological hallmarks of amyotrophic lateral sclerosis (ALS), including mutations in the C9ORF72 gene that characterise the most common genetic form of ALS (C9ALS)." (PMID 40772263, 2025). "The RGG motif forms condensates not only with RNA but also with folded DNA sequences, such as the promoter region of the oncogene c-Myc and the G4C2 repeat of the C9orf72 gene, which has been implicated in amyotrophic lateral sclerosis (ALS)." (PMID 41614783, 2025). "Mutations in the C9orf72 gene represent the most common genetic cause of amyotrophic lateral sclerosis (ALS), a fatal neurodegenerative disease." (PMID 40891053, 2025). "The GGGGCC hexanucleotide repeat expansion (HRE) of the C9orf72 gene is the most frequent cause of amyotrophic lateral sclerosis (ALS), a devastative neurodegenerative disease characterized by motor neuron degeneration." (PMID 39316747, 2024). "Arginine-rich dipeptide repeat proteins (R-DPRs), poly(PR) and poly(GR), translated from the hexanucleotide repeat expansion in the amyotrophic lateral sclerosis (ALS)-causative C9ORF72 gene, contribute significantly to pathogenesis of ALS." (PMID 37332605, 2023). "The aberrant expansion of GGGGCC hexanucleotide repeats within the first intron of the C9orf72 gene represent the predominant genetic etiology underlying amyotrophic lateral sclerosis (ALS) and frontal temporal dementia (FTD)." (PMID 37570771, 2023). "This specific peptide sequence, notorious for its cellular toxicity, is encoded by the C9ORF72 gene, intrinsically linked to amyotrophic lateral sclerosis (ALS)." (PMID 37764485, 2023). "The hexanucleotide G4C2 repeat expansion in C9orf72 is the most frequent genetic cause of familial amyotrophic lateral sclerosis (ALS)." (PMID 37791472, 2023). "A hexanucleotide G4C2 repeat expansion located in the first intron of the C9orf72 gene is the most common genetic cause of both amyotrophic lateral sclerosis (ALS) and FTD." (PMID 37733679, 2023). "Clinical heterogeneity observed across patients with amyotrophic lateral sclerosis (ALS) is a known complicating factor in identifying potential therapeutics, even within cohorts with the same mutation, such as C9orf72 hexanucleotide repeat expansions (HREs)." (PMID 36070099, 2022). "Amyotrophic lateral sclerosis (ALS) is caused by a number of mutations, with C9orf72 repeat expansions the most common genetic cause and SOD1 gain-of-function mutations the first genetic cause identified for this disease." (PMID 33823304, 2022). "Pathogenic NOTCH2NLC expansions have been identified in patients with essential tremor (ETM6, MIM #618866), C9ORF72-associated amyotrophic lateral sclerosis/frontal temporal dementia (ALS/FTD), Parkinsonism, and multiple system atrophy." (PMID 36110216, 2022).